PAK1 (p21 (RAC1) activated kinase 1)
Diseases named in the same sentence as PAK1 in open-access papers (continued):
Sharing a sentence is not in itself a finding about the gene and the disease.
autism (6 papers, 2012 to 2025). Persistent deficits in social interaction and communication and interaction as well as a markedly restricted repertoire of activity and interest as well as repetitive patterns of behavior. "PAK1 inhibitors can rescue some deficiencies associated with NDDs, including the neurofibromatosis model of autism, fragile X syndrome, and schizophrenia." (PMID 37124926, 2023). "PAK1 inhibitors are known to markedly improve social and cognitive function in several animal models of brain disorders, including autism, but the underlying mechanisms remain elusive." (PMID 27296803, 2016). "Exactly how PAK1 activation controls brain development, and why specific chromatin remodeler components, e.g., BAF170 encoded by SMARCC2 in autism, await clarification." (PMID 37124926, 2023). "For example, PAK1 deletion has been shown to normalize synaptic and behavioral deficits in the Neurofibromatosis model of autism." (PMID 27296803, 2016). "With respect to neurodevelopmental disorders, such as autism, these data could have significant implications for both the therapeutic potential of PAK1 inhibitors or agents that enhance AEA signaling." (PMID 27296803, 2016).
cardiac arrhythmia (6 papers, 2014 to 2023). Any disturbances of the normal rhythmic beating of the heart or MYOCARDIAL CONTRACTION. "Significant progress has been made in understanding the role of Pak1 and Ca2+ homeostasis in the pathogenesis of cardiac arrhythmias." (PMID 39899001, 2022). "Finally, we proposed a new and exciting route for developing a PAK1-based therapeutic strategy for cardiac arrhythmias." (PMID 37122206, 2023). "In addition, PAK1 plays a crucial role in multiple cardiovascular diseases, including cardiac arrhythmias, cardiac contractility dysfunction, hypertrophy, and I/R." (PMID 34603600, 2021). "PAK1 plays a key role in cardiac diseases including pressure overload and adrenergic stress-induced hypertrophy and ischemia/reperfusion injury, as well as disrupted Ca2+ homoeostasis-related cardiac arrhythmias." (PMID 33796531, 2021).
endometrial cancer (6 papers, 2015 to 2025). Primary or metastatic malignant neoplasm involving the endometrium (mucous membrane that lines the endometrial cavity). "Overexpression of PAK1 promotes endometrial cancer progression and cell proliferation and previous studies have demonstrated that it is overexpressed in clinical samples of endometrial cancer when compared with normal endometrium." (PMID 41284888, 2025).
Insulin resistance (6 papers, 2022 to 2025). Increased resistance towards insulin, that is, diminished effectiveness of insulin in reducing blood glucose levels. "PAK1 deficient (PAK1+/− and PAK1−/−) mice developed severe peripheral insulin resistance under normal chow-fed conditions." (PMID 37759961, 2023). "Enlarged lipid droplets are often associated with insulin resistance, and as Pak1 is crucial for maintaining insulin sensitivity and glucose metabolism, its dysfunction could also contribute to lipid droplet enlargement and adipocyte hypertrophy." (PMID 40065530, 2025). "Human T2D and insulin resistance are associated with impaired skeletal muscle mitochondrial function, decreased expression of oxidative metabolism genes and proteins, reduced mitochondrial size and copy number, and reduced levels of PAK1." (PMID 37759961, 2023). "Our analysis showed that some of the pathways activated predominantly at the 4 h time point in HG conditions have direct roles in mediating blood glucose homeostasis and have been implicated in insulin resistance, particularly PAK1, HGF, BMP and IGF-1 signaling pathways." (PMID 36463298, 2022). "To determine how PAK1 enrichment had the ability to ameliorate mitochondrial dysfunction and structural damage mediated by insulin resistance in skeletal myotubes, we evaluated the mRNA and protein levels of PGC1α in these myotubes." (PMID 37759961, 2023). "Given that PAK1 depletion in mouse skeletal muscle leads to insulin resistance and glucose intolerance, we sought to examine if PAK1 enrichment would promote insulin sensitivity and enhance glucose tolerance." (PMID 35222279, 2022). "In addition, insulin activates the group I p21-activated kinase (PAK) isoforms PAK1 and PAK2, and PAK1/2 signaling was impaired by insulin resistance in skeletal muscle." (PMID 36942499, 2023). "Moreover, PAK1 enrichment in GLUT4-myc-L6 myoblasts preserves normal insulin-stimulated GLUT4 translocation under insulin resistance conditions." (PMID 35222279, 2022). "Because PAK1 protein levels are reduced in skeletal muscle from T2D individuals, we used hPAK1-overexpressing L6-GLUT4-myc myoblasts exposed to chronic insulinemia (5 nM insulin for 12 h) as a model of insulin resistance." (PMID 35222279, 2022).
schizophrenia (6 papers, 2012 to 2025). A major psychotic disorder characterized by abnormalities in the perception or expression of reality. "The increase in pMLC levels in the ACC has been linked to the shrinkage of the dendritic spine, suggesting a PAK1-related mechanism that regulates dendritic spine loss in schizophrenia." (PMID 33306168, 2022). "In addition, human psychiatric diseases like schizophrenia or bipolar disorder can be caused by alterations in genes with high similarity to Pak (PAK1/2/3) and dbo (KLHL20 indirect, via regulation of Pak,)." (PMID 37759179, 2023). "Of those proteins known to regulate actin stabilization, p21-activated kinase 1 (PAK1) is a plausible point of dysregulation contributing to a reduction in dendritic spines in schizophrenia, a premise supported by multiple lines of evidence." (PMID 23613712, 2013). "We utilized quantitative western blotting to measure PAK1 levels in post mortem auditory cortex gray matter samples from 25 schizophrenia subjects and matched controls in whom we had previously measured kalirin isoform levels." (PMID 23613712, 2013). "This study sought to determine if there is decreased auditory cortex PAK1 protein expression in schizophrenia through the use of quantitative western blots of 25 schizophrenia subjects and matched controls." (PMID 23613712, 2013). "Spinophiln protein levels, like PAK1 levels, were unchanged in subjects with schizophrenia (t18 = 0.58, p = 0.57)." (PMID 23613712, 2013). "The distribution of PAK1 level was evenly distributed among schizophrenia and control subjects with 48% of schizophrenia subjects and 52% of control subjects having higher PAK1 levels." (PMID 23613712, 2013). "We hypothesized that altered PAK1 protein expression may contribute to the reduction in dendritic spine density in the auditory cortex of schizophrenia subjects." (PMID 23613712, 2013). "Although there was no overall change in mean PAK1 protein levels in our subjects with schizophrenia, within pair differences in PAK1 levels were correlated with those of an upstream effector, total kalirin, and with levels of a dendritic spine marker, spinophilin." (PMID 23613712, 2013). "p21-activated kinase 1 (PAK1) regulates both the actin cytoskeleton and dendritic spine density, and is a downstream effector of both kalirin and CDC42, both of which have altered expression in schizophrenia." (PMID 23613712, 2013). "While PAK1 fulfills all of these criteria and is stable in postmortem tissue, this study demonstrated that there is no change in PAK1 protein expression in whole grey matter extracted from the auditory cortex of schizophrenia subjects in our cohort." (PMID 23613712, 2013). "PAK1 protein level was not significantly different between the schizophrenia subjects and matched controls in our cohort (t22.7 = −0.79, p = 0.44)." (PMID 23613712, 2013). "These latter two findings suggest that the lack of change in PAK1 level in schizophrenia is not due to limited sensitivity of our assay to detect meaningful differences in PAK1 protein expression." (PMID 23613712, 2013). "Future studies are needed to evaluate whether alterations in PAK1 phosphorylation states, or alterations in protein expression of other members of the PAK family, are present in schizophrenia." (PMID 23613712, 2013). "There was no significant change in PAK1 level detected in the schizophrenia subjects in our cohort." (PMID 23613712, 2013).
colitis (5 papers, 2019 to 2025). Inflammation of the colon. "There, loss of PAK1 exacerbated colitis and tumorigenesis, displaying a distinct intestinal epithelial hyperproliferative phenotype with elongated crypts and loss of goblet cells." (PMID 40783411, 2025). "Perhaps it is a matter of timing, and PAK1 overexpression is protective prior to the damaging event, or just in this specific model of colitis." (PMID 40783411, 2025). "Modulation of the immune response upon AOM/DSS colitis may be a further mechanism that PAK1 overexpression could be protective in our study." (PMID 40783411, 2025). "However, in IL10KO mice, another mouse model of IBD, Pak1 deletion exacerbates colitis and tumorigenesis." (PMID 40783411, 2025). "Apart from the previous study where PAK1 loss impaired tumor initiation in AOM/DSS models7our group also had a study where we crossed PAK1KO with IL10KO, a mouse model of IBD which develops spontaneous colitis." (PMID 40783411, 2025). "We were surprised to find that floxing of Pak1 alone reduced inflammation in both chronic and acute models of DSS colitis." (PMID 40783411, 2025). "This suggests that floxing itself may have altered Pak1, which conferred protection from colitis and tumorigenesis upon AOM/DSS, but not from colitis upon total loss of IL10." (PMID 40783411, 2025).
COVID-19 (5 papers, 2021 to 2023). A disease caused by infection with severe acute respiratory syndrome coronavirus 2. "It has been shown that ciclesonide inhibits the enzyme PAK1, a pathogenic pathway for COVID-19 related to ACE2: by inhibiting PAK1, ciclesonide reduces immune suppression and reduces lung inflammation." (PMID 35745708, 2022). "Thus, PAK1-blockers, interfering with the pathogenic process, could act as potential therapeutic agents for COVID-19 patients." (PMID 36339607, 2022). "PAK1 is an important “pathogenic” kinase whose abnormal activation is responsible for various disorders including cancers, HIV, and COVID-19." (PMID 36339607, 2022). "In summary, we show that PAK1 is an attractive host factor that may be targeted for the therapeutic purpose of COVID-19." (PMID 37806990, 2023). "Moreover, Artepillic C, a major ingredient of Brazilian propolis, was found to be responsible for the inhibition of p21-activated kinase 1 (PAK1), a protein involved in the pathogenesis of many diseases including COVID-19." (PMID 34576987, 2021). "The same propolis ingredient, Artepillic C, was shown to block activation of PAK1 (RAC/CDC42-activated kinase 1), the enzyme responsible for cancer, inflammation, malaria, influenza, HIV and COVID-19." (PMID 34576987, 2021).
developmental delay (5 papers, 2021 to 2025). "The patient exhibited global developmental delay, seizures, hypotonia, and macrocephaly, indicating that this activating mutation in the kinase domain of the PAK1 protein disrupts normal neuronal development and contributes to a neurodegenerative phenotype." (PMID 41516310, 2025). "A previous study reported two unrelated subjects who had de novo c.392A > G (p.Tyr131Cys) and c.1286A > G (p.Tyr429Cys) variants in PAK1 gene exhibited developmental delay, macrocephaly, seizures, and ataxic gait." (PMID 36624491, 2023). "The PAK proteins, PAK1 and PAK3, are central regulators of neuronal development and activating PAK1 mutations were aetiologic for secondary macrocephaly, developmental delay, ataxic gait and seizures in two unrelated patients." (PMID 34111223, 2021).
fragile X syndrome (5 papers, 2012 to 2025). A genetic syndrome caused by mutations in the FMR1 gene which is responsible for the expression of the fragile X mental retardation 1 protein. "Therefore, the ability of the PAK1 inhibitors in ameliorating the deficits associated with models of fragile X syndrome and neurofibromatosis may be mediated by its effect on the GABA function." (PMID 27296803, 2016). "In models of synaptopathy, PAK1 knockout (KO) in Fragile X syndrome (FXS) mice rescued synaptic and cognitive deficits—a finding further supported by pharmacological inhibition using non‐selective PAK inhibitors." (PMID 41451871, 2025).
Hypertension (5 papers, 2015 to 2024). The presence of chronic increased pressure in the systemic arterial system. "Pak1 plays a pathogenic role in cancer, infectious diseases (AIDS, malaria and flu), inflammatory diseases (asthma and arthritis), insulin-resistant diabetes (type 2), hypertension, obesity, and other diseases, and thus, several synthetic drugs that selectively block Pak1 have been developed." (PMID 26506521, 2015). "Theoretically, the inhibitors of PAK1 and PAK2 may also affect vascular function and related diseases; modulating PAK1 and PAK2 activity will be useful in treating dysfunctional vascular problems, such as hypertension, diabetic retinopathy, and cerebrovascular diseases." (PMID 39766303, 2024).
lung adenocarcinoma (5 papers, 2015 to 2023). A carcinoma that arises from the lung and is characterized by the presence of malignant glandular epithelial cells. "Other studies showed Pak1 up-regulation in cancer tissue over normal matched tissue of 2.96-fold in squamous cell lung carcinoma, 2.23-fold in lung adenocarcinoma, and of 2.16-fold in invasive breast carcinoma (TCGA invasive breast)." (PMID 26555075, 2015). "We analyzed the prognostic impact of PKC, PAK1, and GSK3B in patients with lung adenocarcinoma and squamous lung cancer." (PMID 38017514, 2023).
Macrocephaly (5 papers, 2021 to 2025). Occipitofrontal (head) circumference greater than 97th centile compared to appropriate, age matched, sex-matched normal standards. "Pathogenic PAK1 variants were described to be causative of neurodevelopmental disorder with macrocephaly, seizures, and speech delay." (PMID 36624491, 2023). "Causative variants in PAK1 gene were related to intellectual developmental disorder with macrocephaly, seizures, and speech delay (IDDMSSD; 618,158)." (PMID 36624491, 2023). "Pathogenic variants in PAK1 cause an autosomal dominant form of intellectual developmental disorder with macrocephaly, seizures, and speech delay (IDDMSSD, OMIM # 618158)." (PMID 34943902, 2021). "Thus, the clinical feature of macrocephaly may manifest incomplete penetrance in patients with PAK1 variants." (PMID 36624491, 2023). "To date, five PAK1 mutations affecting the Ser110, Pro121, Tyr131 and Ser133 residues were thus identified in the AID and associated with ASD, ID and macrocephaly." (PMID 36937657, 2023). "PAK1 is a common interactor to RAC1 and RAC3, and is associated with an autosomal dominant NDD known as intellectual developmental disorder with macrocephaly, seizures, and speech delay (IDDMSSD, OMIM # 618158)." (PMID 34943902, 2021).
Obesity (5 papers, 2015 to 2025). Accumulation of substantial excess body fat. "While reduced human skeletal muscle PAK1 and Rac1 activation levels are associated with T2D and obesity, these are correlations that require testing to ascertain whether skeletal muscle-specific depletion of PAK1 is sufficient to impair glucose homeostasis by dampening GLUT4 translocation." (PMID 35222279, 2022). "These sex‐specific differences point to the need for further research on Pak1's role in human heart aging and obesity, particularly in postmenopausal women." (PMID 40065530, 2025). "Consistent with this concept, PAK1 signaling impairments in skeletal muscle have been correlated with obesity and T2D, indicating the significance of PAK1 in both insulin-dependent glucose uptake pathways in skeletal muscle." (PMID 29209279, 2017). "Taken together, these studies highlight the critical role of Pak1 in regulating glucose metabolism, insulin sensitivity, and β‐cell survival, positioning Pak1 as a promising therapeutic target for T2D in addition to its promise as a target for obesity and cardiac dysfunction." (PMID 40065530, 2025).
osteosarcoma (5 papers, 2015 to 2023). A usually aggressive malignant bone-forming mesenchymal neoplasm, predominantly affecting adolescents and young adults. "This study further confirmed an oncogenic role for Pak1 expression in osteosarcoma." (PMID 26555075, 2015). "Several candidate osteosarcoma oncogenes found in a transposon-based forward genetic screen in mice are also hypomethylated and overexpressed in human osteosarcoma compared to normal osteoblasts, including SEMA4D, RAF1 and PAK1." (PMID 29056713, 2016). "In addition, some potential downstream genes of miR-30b-3p, such as ATG5, PAK1, FOXP4, and MYO10 also exerted crucial roles in osteosarcoma." (PMID 35123530, 2022). "Due to the low incidence of osteosarcomas, which represents less than 1% of all the cancers diagnosed in the United States, no data on Pak1 expression on osteosarcomas were found in public databases." (PMID 26555075, 2015). "Due to the low incidence of osteosarcomas, which represents less than 1% of all the cancers diagnosed in the United States, no data on Pak1 expression on osteosarcomas were available." (PMID 26555075, 2015).
skin cancer (5 papers, 2016 to 2025). "One intriguing finding of our study was the presence of structural variants in PAK1, particularly in breast and skin cancers, where these alterations were associated with worse clinical outcomes." (PMID 39756822, 2025). "Moreover, in skin cancer specifically, PAK1 and PAK4 promote cell invasion of uveal melanoma and SCC cell lines, respectively." (PMID 27765920, 2016).
squamous cell lung carcinoma (5 papers, 2015 to 2026). A carcinoma arising from squamous bronchial epithelial cells. "CD44/PAK1/AKT activation may help predict the response to FGFR1 inhibition in squamous cell lung cancer." (PMID 41459112, 2026). "The Combination of PKCι-PAK1 inhibitors was highly synergistic in EGFR and KRAS mutant adenocarcinoma and squamous cell carcinoma of the lung, in both in vitro and in vivo mice models." (PMID 31660987, 2019).
type 2 diabetes (5 papers, 2017 to 2025). "The human gene encoding p21 (CDC42/Rac1)-activated kinase 1 (PAK1) resides within the type 2 diabetes susceptibility locus on chromosome 11." (PMID 39404845, 2025). "Beta cell-specific PAK1 enrichment in type 2 diabetes human islets resulted in decreased beta cell apoptosis and increased insulin content." (PMID 39404845, 2025). "Gene ontology (GO) analysis was performed to define the biological processes enriched by PAK1 overexpression in human type 2 diabetes islets." (PMID 39404845, 2025). "Given the heterogeneous and progressive nature of type 2 diabetes, we evaluated PAK1 regulation of insulin biogenesis-related genes under baseline conditions and performed RNA-seq analysis using PAK1-overexpressing ND human islets." (PMID 39404845, 2025). "PAK1 is downregulated in islets from type 2 diabetes donors, which prompted us to follow up PAK1 in human islets." (PMID 39280605, 2024). "Thus, PAK1-dependent increase in insulin biogenesis genes may be context-dependent, as observed in type 2 diabetes." (PMID 39404845, 2025). "Further, exogenous PAK1 induction reduced CC-3 and increased BCL2 (anti-apoptotic marker) in type 2 diabetes human islets." (PMID 39404845, 2025). "We found that the abundances of PAK1 protein and its downstream effector in muscle, ARPC1B, are significantly reduced in the skeletal muscle of humans with type 2 diabetes, compared to the non-diabetic controls, making skeletal muscle PAK1 a candidate regulator of glucose homeostasis." (PMID 35222279, 2022).